SDHC (succinate dehydrogenase complex subunit C)
Diseases named in the same sentence as SDHC in open-access papers (continued):
Sharing a sentence is not in itself a finding about the gene and the disease.
tumor (continued). "In pooled differential expression analyses between healthy and tumor samples more proteins were downregulated, while several proliferation-related proteins (e.g., POL2RK, MEN1, MNAT1, TAF9, or SDHC) and biological processes were upregulated." (PMID 38802361, 2024). "Accordingly, we observed up-regulation of the Succinate dehydrogenase complex, a tetramer consisting of SDHA, SDHB, SDHC and SDHD subunits that exerts a critical tumor suppressive role and has been proposed as an important therapeutic target in HCC." (PMID 36203462, 2022). "Notably, the location of PPGL in patients with germline SDHx mutations or SDHC epimutations can be anywhere from the skull base to the pelvis and dSDH PPGL also have a high malignant potential, increasing the risk for synchronous malignant primary tumours in one individual." (PMID 33443647, 2021). "We aslo analyzed the differential expression of PGK1, SDHC, PFKL, and NUP43 in tumor and normal samples." (PMID 33584825, 2021). "Further studies about the relationship of SDHC, SDHD, MTCO3, and NDUFV3 in MQ-induced anti-tumor effect will be applied." (PMID 32850358, 2020). "Moreover, SDHC may play an important role in the MQ-induced anti-tumor effect of ESCC." (PMID 32850358, 2020). "The results of RT-PCR analysis as well as bioinformatics analysis consistently demonstrated that the expression of RWDD4, SDHC, SEPT7, and SFN was downregulated in the tumor tissues as compared with that in adjacent non-tumor tissues." (PMID 32156290, 2020). "It is now recognized that in a subset of dSDH tumours, SDH inactivation results from promoter hypermethylation and epigenetic silencing of the SDHC gene." (PMID 31308404, 2019). "Our findings was supported by previous studies showing that the expression of SDHC and SDHD was reduced in tumor tissues and their roles as tumor suppressors have been identified." (PMID 26377099, 2015). "Despite the two PTC tumors with SDHC duplication showing increased SDHC mRNA expression, significantly reduced transcript expression of SDHC and SDHD was observed in the tumor samples compared with their paired normal tissue (both P<0.001)." (PMID 25694510, 2015). "This would be a requirement specific for SDHD, as tumor development in SDHB, SDHC and SDHA appear to follow a two-hit kinetics." (PMID 24465590, 2014). "Multiple other genes encoding enzymes of the tricarboxylic (TCA) cycle are considered tumor suppressor genes including SDHB, SDHC, and SDHD (Succinate Dehydrogenase subunits B,C,D)." (PMID 21695080, 2011). "To explore the potential mechanisms, we conducted drug screening and RNA sequencing, and found that SDHC may affect lipid metabolism through the PI3K/AKT signaling axis, thus regulating tumor metastasis." (PMID 38844980, 2024). "Tumour cells lacked SDHB staining at IHC but expressed SDHA; preserved SDHA IHC being a recognised phenomenon in SDHB, SDHC and SDHD pathogenic variants." (PMID 35938916, 2022). "123I-MIBG and 111In-pentetreotide scintigraphy should not be used as first-line imaging studies for initial tumour screening in asymptomatic SDHA, SDHB, SDHC or SDHD-pi mutation carriers (Grade A)." (PMID 34021277, 2021). "In 5/5 tumour samples with SDHC hypermethylation the mean fold difference was −6.41(SD 5.4) compared to 1.41 (SD 4.41) in 26 tumours without SDHC hypermethylation (P = 0.0002)." (PMID 31308404, 2019). "There were no LOH at coordinates corresponding to SDHC loci in tumours from patients with germline SDHC Pro110Ser and Met164Leu variants." (PMID 24466223, 2014).
tumor (continued). "Importantly, the expression of SDHB is lost in all SDH-deficient neoplasms irrespective of the specific SDH subunit (SDHA, SDHB, SDHC, and SDHD) affected by a genetic mutation." (PMID 37999735, 2024). "Therefore, SDHB-absent tumor immunostaining suggests the presence of an inactivating germline SDHA, SDHB, SDHC, or SDHD followed by a somatic loss in the second allele of the gene." (PMID 36091175, 2022). "The tumor cells of SDHB-, SDHC-, and SDHD-mutated tumors were reported to show absence of SDHB immunostaining, whereas those of non-SDH mutated tumors showed strong SDHB immunostaining, and SDHB immunohistochemistry was found to have 100% sensitivity and 84% specificity in detecting mutations." (PMID 35300626, 2022). "To investigate whether the anti-tumor effect of MQ are SDHC dependent or not in vivo, we established PDX mouse models of ESCC." (PMID 32850358, 2020). "Therefore, when we showed that SDHC was downregulated in MQ-treated ESCC cells, we hypothesized that SDHC may play an important role in ESCC tumor growth." (PMID 32850358, 2020). "Knockdown of pdsw, but not ATPsynβ, sdhC or cox5A, abrogated Hipk-induced tumor-like growth." (PMID 33199523, 2020). "Interestingly, MQ significantly suppressed tumor growth of PDXs with high level of SDHC, while not having the same effect in PDXs with low level of SDHC." (PMID 32850358, 2020). "None of the tumours showed evidence of SDHC promoter hypermethylation." (PMID 31308404, 2019). "With improved understanding of the factors regulating SDHC alternative splicing, it may be possible to limit the tumor cell growth potential by promoting the production of non-functional or dominant-negative types of SDHC ASVs." (PMID 25435987, 2015). "Unfortunately, we could not find reliable SDHC/D antibodies to measure protein expression of these two subunits in our tumor samples." (PMID 25694510, 2015).
cancer (28 papers, 2010 to 2025). A tumor composed of atypical neoplastic, often pleomorphic cells that invade other tissues. "It has also been reported that the mutation rate of SDHC was higher among the succinate dehydrogenase complex subunits in cancer." (PMID 32850358, 2020). "These included the following genes known for their association with cancer: BRAF (V600E) and PIK3CA (E545K), both harboring hotspot mutations and three other possible driver genes, SDHC (H127R), DDR2 (R668C), and FANCD2 (C1130Y)." (PMID 34301805, 2021). "More studies on tumors, patients, and families are needed to inform whether SDHA pathogenic variants are associated with a specific cancer risk profile compared with SDHB, SDHD, or SDHC." (PMID 38885448, 2024). "Regarding those genes involved in germline predisposition to other cancers, ATM, APC, POLD1 or SDHC could be promising candidate genes for germline GC predisposition." (PMID 33525650, 2021). "These cancers also depend on a set of hemoproteins, such as cytochrome c-1 (CYC1), succinate dehydrogenase complex subunit C (SDHC) for cellular respiration, and DGCR8 for microRNA biogenesis, each of which uses heme as a co-factor." (PMID 38649187, 2024). "After assessing SDHs differential expression in pan-cancer, we found that SDHB, SDHC, and SDHD benefit COAD patients." (PMID 36949947, 2023). "In the current study, SDHC ASV was found to have a dominant-negative effect on SDHC activity, which provides a new possible target for cancer therapy." (PMID 25435987, 2015). "This is the first example of active oxygen generated from an SDHC ASV, which directly affects cancer cell formation." (PMID 25435987, 2015). "Of the 27 patients who presented with multiple PGLs at the time of their genetic counseling consultation, 24 completed genetic testing and 19 (79.2%) tested positive for an LPV/PV in a hereditary cancer gene, all of which were in PGL/PCC genes (SDHD = 13, SDHB = 4, SDHC = 2)." (PMID 39539798, 2024). "Third, from our in silico gene deletion analysis, we identified Sterol O-Acyltransferase 1 (SOAT1), methylmalonyl-CoA mutase (MUT), and isozymes of succinate dehydrogenase (SDHA, SDHB, SDHC, and SDHD) as having a significant effect (p-value < 0.05) in cancer as compared to normal samples." (PMID 33396819, 2020). "This was particularly evident in carcinomas of basal-like molecular subtype compared to non-basal-like tumors, and a low SDHC expression level tended to have a prognostic impact in those patients." (PMID 31164982, 2019).
infection (3 papers, 2016 to 2023). The state of being infected such as from the introduction of a foreign agent such as serum, vaccine, antigenic substance or organism. "Mouse competitive infection assays further validated the involvement of fepB, sdhC, fepG, gltS, dcuA, ccmH, ddpD, narU, glpD, malM, and yabL in in vivo fitness." (PMID 36537189, 2023). "sdhC is known to contribute to the pathogenicity of bacteria, but its role in infection has yet to be elucidated." (PMID 26870007, 2016). "However, the competitive infection assay showed that the deletion of sdhC significantly compromised the ability of ExPEC to colonize the brain, spleen, and lung." (PMID 36537189, 2023).
neurodegenerative disease (1 paper, 2015). A disorder of the central nervous system characterized by gradual and progressive loss of neural tissue and neurologic function. "The prevalent pathways that were differentially affected during male ageing relate to neurodegenerative diseases such as HD, AD, and PD; in this case, the implicated genes (CASP7, CALM3, CYCS, SDHC, multiple subunits of Complex I, Complex IV, and ATP synthase) are downregulated." (PMID 25977747, 2015).
SDHC also shares sentences with these, for which no sentence is quoted: neurofibromatosis type 1 (5 papers); multiple endocrine neoplasia type 2 (4); pituitary adenoma (4); bladder cancer (2); genetic disease (2); mitochondrial disease (2); tumor predisposition syndrome (2); acromegaly (1); adrenocortical adenoma (1); alveolar soft part sarcoma (1); Alzheimer disease (1); anaplastic astrocytoma (1); breast invasive carcinoma (1); carotid body paraganglioma (1); chondroma (1); Cowden syndrome (1); endocrine tumors (1); Ewing sarcoma (1); familial focal epilepsy (1); glioblastoma (1); hereditary leiomyomatosis and renal cell cancer syndrome (1); Hodgkins lymphoma (1); Huntington disease (1); hyperparathyroidism (1); kidney cancer (1); lipoma (1); lobular carcinoma (1); lung carcinoma (1); malignant peripheral nerve sheath tumor (1); mammary adenocarcinoma (1).
A further 22 diseases each share a sentence with SDHC in 1 paper.